CD4 (CD4 molecule)
Diseases named in the same sentence as CD4 in open-access papers (continued):
Sharing a sentence is not in itself a finding about the gene and the disease.
eosinophilia (continued). "Secondly, CD3+, CD4+ and CD8+ T lymphocytes from naïve CD3IL-5+ and C57BL/6 mice were adoptively transferred to immunodeficient SCID-bg mice to determine their effect on BM eosinophilia." (PMID 16740158, 2006). "The role of DLCO in the evaluation of SSc-ILD patients may be highlighted: the decrease in DLCO correlates not only with the presence of neutrophilia or eosinophilia on BAL, but also with the BAL CD19 percentage count, inverted CD4/CD8 ratio, and CCL-18 concentrations." (PMID 36559035, 2022). "This sustained eosinophilia in the absence of CD4+ T cells may be explained by the ability of IL-27 to inhibit proliferation and cytokine production by type 2 innate lymphoid cells (ILC2s)." (PMID 28129374, 2017). "In addition, in our study the CD4+ T-cell count of those identified with eosinophilia was not significantly different from those with normal eosinophil count (mean [SD] (324 versus 384, p = 0.37)." (PMID 24010677, 2013). "Interestingly, we measured substantial increases in IL-4, IL-5, IL-13, and IL-17 from restimulated CD4+ T cells as well as substantial increases in eosinophilia and neutrophilia in the BAL, indicating that our one sensitization model polarizes CD4+ T cells down both Th2 and Th17 pathways." (PMID 20659336, 2010). "Additionally, CD3+, CD4+ or CD8+ T lymphocytes from naïve CD3IL-5+ and wild type C57BL/6 mice were adoptively transferred to immunodeficient SCID-bg mice, in order to determine their role in regulating BM eosinophilia." (PMID 16740158, 2006). "By age 4, immunological studies demonstrated normal mitogen and pathogen response, normal CD4 and CD8 levels, eosinophilia, low IgM, and an absent IgG response to tetanus and candida." (PMID 34938854, 2021). "Areas that warrant further research include serologic test performance in migrant PLWHA living in non-endemic settings and the degree of eosinophilia in relation to markers of HIV control, including CD4 count and VL." (PMID 31992216, 2020). "Both CD4+T and CD8+T cells from Ad5-gsgAM- but not Ad5-immunized mice significantly reduced eosinophilia." (PMID 29302700, 2018). "In the presence of poly IC, eosinophilia, IL-13 in BALF, and the numbers of IL-13-producing CD4+ and CD8+ T cells were augmented in Kit+/+ mice but not in KitW/KitW-v mice." (PMID 23452625, 2013). "Adoptive transfer of CD8+, but not CD4+ T lymphocytes from naïve CD3IL-5+ and C57BL/6 mice restored BM eosinophilia in immunodeficient SCID-bg mice." (PMID 16740158, 2006). "Although therapeutic αIFN-γ did not restore eosinophilia in Il10ΔCD4 mice, it reduced numbers of neutrophils (see Fig E7, B and C) and IFN-γ+ CD4+ T cells in BAL fluid to levels comparable with those in Il10fl/fl control mice, suggesting that IFN-γ promotes airway inflammation in these mice." (PMID 31445933, 2020). "Indeed, depletion of CD4+ cells just before final allergen challenge or genetic ablation of IL-17A/F compromised CXCL5 accumulation and allergic neutrophilia, but not eosinophilia, in the airways of LH mice despite their extensive inhalation experience." (PMID 39965565, 2025).
leishmaniasis (116 papers, 2009 to 2025). Infectious disease that is transmitted through the bite of hematophagous female phlebotomine sand flies. "The CD4+ T cell responses seen in leishmaniasis patients depend on the causative species and the site of infection." (PMID 39781380, 2024). "Of note, the mean CD4 count for nearly all cohorts was less than 200, a finding clearly carrying increased risk of leishmaniasis clinical manifestations." (PMID 36427170, 2023). "Severe lesions are reported in L. major-infected WSX-1−/− mice, which were associated with the appearance of the IL-17+ CD4+ cells, indicating a role for IL-27 in preventing the improper development of Th17 cells during Leishmaniasis." (PMID 32849534, 2020). "The inability to mount an effective response in dogs with leishmaniasis occurs due to T lymphocyte exhaustion, involving loss of ability to perform CD4 and CD8 effector cell functions." (PMID 31961868, 2020). "Leishmaniasis is caused by intracellular Leishmania parasites that induce a T-cell mediated response associated with recognition of CD4+ and CD8+ T cell Line 1Lineepitopes." (PMID 25905908, 2015). "Briefly, resistance to leishmaniasis has been associated with a predominant IFN-γ production from the antigen-specific CD4+ T lymphocyte population-termed T helper 1 (Th1) immune response." (PMID 25889286, 2015). "CD4+ T lymphocytes and monocytes are key cells in the protection against leishmaniasis; however they have been associated to the inflammatory process and tissue lesion in the cutaneous form of disease." (PMID 23209879, 2012). "In the Th1 response to leishmaniasis, promastigotes attach to reticuloendothelial cells, causing CD4+ cells to produce IL-2, IL-3 and IFN-γ." (PMID 20927287, 2010). "A report from New World leishmaniasis showed that in both asymptomatic and antimonial treated CL individuals caused by L. braziliensis, a higher proportions of CD4+ than CD8+ T cells was present." (PMID 20967288, 2010). "Hence, pro-inflammatory cytokines commonly associated with host protection in leishmaniasis and many other infectious diseases can also drive the development of pathogenic CD4+ T cells that cause long term irreversible alterations in HSC function." (PMID 28671989, 2017). "Furthermore, in experimental and human tegumentary leishmaniasis, data reinforce the pathogenic role of CD4+ cells in lesion development of leishmaniasis." (PMID 20459816, 2010). "However, the association of IFNγ+IL-10+ CD4+ T cells with disease progression in leishmaniasis has suggested that through IL-10 production, these cells may contribute to parasite persistence and/or disease pathology." (PMID 22911108, 2012). "PEPCK335–351, which has been found to elicit polyfunctional CD4+ T cell responses and provide good protection against leishmaniasis, was used as a control for our analysis." (PMID 40134009, 2025). "Leishmaniasis is an immunosuppressive disease, where CD4 secreting IFN-γ cells have been shown to be required for parasite control, and IL-10 levels are related to parasite persistence." (PMID 40737310, 2025). "Control of leishmaniasis is mediated by CD4+ T cells producing IFN-γ to augment microbicidal activity of parasitized phagocytes (5, –, 7)." (PMID 40741972, 2025). "In leishmaniasis, the skin houses resident CD4+ T cells capable of producing IFN-γ upon restimulation." (PMID 38469319, 2024). "In experimental leishmaniasis, lesions harbor both CD4+ T cells that lack CD69 expression presumably in traveling through the tissues and a separate group of resident T cells expressing the CD69 marker." (PMID 38469319, 2024). "CD8+ T cells transferred in the absence of CD4+ T cells are more pathological than CD8+ T cells co-transferred with CD4+ T cells because CD4+ Th1 cells and CD4+ T regulatory dampen the immune response during leishmaniasis." (PMID 38709823, 2024).
leishmaniasis (continued). "Evidence shows that both antigen-specific IFN-γ-producing CD4+ and CD8+ T cells contribute to the immunity against human leishmaniasis, though the role of CD4+ T cells with two arms of Th1 and Th2 cells has more been highlighted in the outcome of disease." (PMID 38469319, 2024). "Sm29 has been demonstrated to suppress inflammatory responses in leishmaniasis by increasing the numbers of CD4+CD25 and CD4+CTLA-4+ T cells, leading to increased levels of IL-10." (PMID 39481080, 2024). "The role of CD8+ T cells in leishmaniasis has received relatively less attention compared to CD4+ T cells." (PMID 39587036, 2024). "Seder and colleagues (2008) proposed a model for the development of the CD4+ Th1 response in leishmaniasis, which involved the expression of different combinations of three proinflammatory cytokines: IL-2, TNF-α, and IFN-γ." (PMID 38410517, 2024). "Predictors used here revealed that almost twice as many epitopes of sLnAg bind to HLA II molecules than to HLA I molecules, which is expected since the CD4+ T cell response is predominant in leishmaniasis because of intravesicular infection." (PMID 37514945, 2023). "En todos los casos de leishmaniasis, los recuentos de CD4 fueron menores de 100 células/mm3, pero sin una relación estadísticamente significativa." (PMID 35867921, 2022). "Saponins have been extensively used as adjuvants in leishmaniasis vaccines, successfully triggering a Th1-type response and activation of both CD4+ and CD8+ T cell-subtypes in immunized dogs and in a mouse model." (PMID 35891310, 2022). "Healing in leishmaniasis depends on the generation of CD4 + Th1 cells, which produce IFN-γ, with subsequent activation of macrophages to kill intracellular parasites." (PMID 36102970, 2022). "IL-27 induces CD4+ T cell-derived IL-10, which is canonical disease-enhancer in leishmaniasis, whilst at the same time it suppresses Th17/IL-17, both of which can promote disease progression when present." (PMID 33415318, 2020). "Components of innate and adaptive immunity, such as phagocytic cells, natural killer (NK), CD4+, CD8+ lymphocytes and regulatory T cells (Treg), are associated with the control of leishmaniasis." (PMID 31393896, 2019). "Protection against leishmaniasis, in the murine model, is dependent on developing a potent CD4+ mediated Th1 type response." (PMID 31579449, 2019). "Protection against leishmaniasis, at least in the murine model, is dependent on developing a potent CD4+ mediated Th1 type reaction specified by the elevated titers of IgG2a, activation of the CD8+ T cell population, and high level of IFN-γ generation." (PMID 31579449, 2019). "Comparing C57BL/6 ctrl mice (partially resistant) to BALB/c ctrl mice (susceptible), C57BL/6 mice exhibited higher numbers of IFN-γ-producing CD4+ cells, which are related to leishmaniasis control." (PMID 31024859, 2019). "Immunity to leishmaniasis requires selective T cell responses, with immunization schemes that raise either CD4 or CD8 T cell responses being protective in small animal models." (PMID 30386348, 2018). "The present study is in concordance with the study where immunization of BALB/c mice with NH36 DNA vaccine resulted in two to five-fold increase in IFN-γ producing CD4(+) T cells against leishmaniasis." (PMID 29963081, 2018). "Our results match with the stated protective role of sCD40L in VL and indicate the importance of the CD40-CD40L pathway in early human immune responses against leishmaniasis, also in CD4+CD40L+ deprived HIV patients." (PMID 30619775, 2018). "Lymphocytes (dermal CD4+ T cells) have been shown to be the main source of IL-10 in the Leishmaniasis-infected murine skin." (PMID 30072966, 2018). "Such cytokine production would aid in the development of functional epitopes-based assays to evaluate the type and maintenance of CD4+ T-cell populations in various leishmaniasis immunization models." (PMID 29312304, 2017).
leishmaniasis (continued). "To determine if the DTH in leishmaniasis was dependent on either CD4+ or CD8+ T cells, we individually depleted each subset in immune mice before challenge with L. major, and then monitored the DTH response and parasite burden over 72 hrs." (PMID 28419151, 2017). "Previously, all of the vaccine approaches against leishmaniasis have focused on the stimulation of the CD4 T cell response and have neglected the important contribution of CD8 T cells." (PMID 28321221, 2017). "To date, first and second generation vaccines for leishmaniasis have been developed to induce primarily CD4+ T cell responses." (PMID 28498840, 2017). "To conclude, despite all the unanswered questions about immunity to leishmaniasis, multifunctional CD4+ and CD8+ T cells are undoubtedly essential in a pro-inflammatory Th1 environment to control the disease." (PMID 27092123, 2016). "Our in silico analysis showed that enolase contains several promiscuous CD4+ T cell epitopes, supporting the idea that it is a prophylactic molecule against leishmaniasis that is capable of inducing Th1 immune responses." (PMID 26906226, 2016). "The degree of protection against various infections including leishmaniasis is predicted by the frequency of polyfunctional CD4+ memory T cells that produce IFN-γ, TNF-α, and IL-2." (PMID 26485398, 2015). "Conventionally, CD4+ T lymphocytes were considered more crucial in containing leishmaniasis but of late, important participatory role of CD8+ T lymphocytes in clearing Leishmania infection has been demonstrated." (PMID 26696979, 2015). "The precise role of human CD4+T cell subsets, their cytokine patterns and the immune response pathways engaged during and after effective leishmaniasis therapy are incompletely understood." (PMID 26485398, 2015). "Leishmaniasis is usually found in HIV patients who have a CD-4+T cell level less than 200 cells/mm3." (PMID 25502442, 2014). "Activation of IFN-γ-producing CD4+ T cells plays a pivotal role in protective immune responses against leishmaniasis." (PMID 24959167, 2014). "Studies in the literature have shown the important role played by CD4 T cells in protection against human leishmaniasis by producing cytokines able to activate the macrophages that kill the parasites." (PMID 25325049, 2014). "The role of Treg cells in leishmaniasis remains controversial, although they seem to be important cells in T CD4+ suppression during VL." (PMID 25268355, 2014). "In other mouse strains and in studies of human leishmaniasis, however, both CD4+CD25−FoxP3− as well as CD4+CD25+FoxP3+ T cells have been implicated in the long-term control of infection and development of sterile immunity." (PMID 23825956, 2013). "This is perhaps not surprising, since a recent study from our laboratory found that rSSP4 induces a population of IL-10/IFN-γ CD4+ double producers T cells, which have also been identified as a major source of IL-10 during infections such as leishmaniasis." (PMID 23509755, 2013). "IL-10-producing DCs have been described in chronic EVL and CD4+ T cells which produce IL-10 (including natural Tregs, Tr-1 and CD4+ Th1 cells) have all been described in various forms of leishmaniasis in mouse and man." (PMID 24363630, 2013). "In the case of leishmaniasis, several studies have been performed to dissect the relevance of CD4+ and CD8+ T cell subsets and their relative role in natural infection, prophylaxis or therapy." (PMID 22715418, 2012). "Resistance in leishmaniasis has been reported to depend on DC-derived IL-12, the inhibition of Leishmania-specific IL-4-secretion by Vβ4Vα8 CD4+ T cells and the induction of a Th1-dominated immune response in vivo." (PMID 22802978, 2012). "It has been also demonstrated that CD4+ T cells that expresses IFNγ and TNFα play an important role in therapy against leishmaniasis." (PMID 22715418, 2012).
leishmaniasis (continued). "While MPL is reported to promote IFN- γ production by Ag-specific CD4+ T cells and skewing the immune response towards Th1 type, liposomal Ag showed protective response against leishmaniasis." (PMID 22206029, 2011). "Mouse models of leishmaniasis have demonstrated that disease outcome depends critically on the balance between effector and regulatory CD4+ T cell responses, something mirrored in descriptive studies of human disease." (PMID 21909452, 2011). "It has been very effective as an adjuvant providing CD4+ T cell help for immunizations against other protozoan infections such as leishmaniasis." (PMID 21129215, 2010). "CD4+ T cells, a major group of T cells, provide protection to the host during leishmaniasis which relies on the expression of various antiparasitic molecules (e.g. reactive oxygen species, nitric oxide) in phagocytic cells that get activated on IFN-γ productions (Ref." (PMID 39587036, 2024). "H2-D is involved in CD8+ T-cell activation and CD4+ Th1 response in leishmaniasis." (PMID 38299832, 2024). "In the self-healing form of the disease in murine models (C57BL/6 or CBA) and also in humans, the protective immune responses against leishmaniasis were expected to be mediated by Th1 response via the production of IFN- by CD4+ T cells and IL-12 by dendritic cells." (PMID 35090305, 2022). "However, the differentiation of naive CD4+ T cells into Th1/2 cytokines is strictly regulated in leishmaniasis, L. donovani infection can induce differential miRNA expression in CD4+ T cells and macrophages." (PMID 33680991, 2021). "Additionally, the role of the PD-1 pathway on CD4+ T cell differentiation should be better elucidated in leishmaniasis, because most of the studies on PD-1 pathway in leishmaniasis, have been focused on studying PD-1 blockade on CD8+ T cell responses." (PMID 34281214, 2021). "In experimental leishmaniasis, P. acnes was used as an adjuvant with native and recombinant Leishmania antigens for mice vaccination that resulted in protective immunity mediated by CD4+ Th1 lymphocytes." (PMID 32194563, 2020). "Various subsets of CD4+ T cells play different roles in leishmaniasis." (PMID 32784615, 2020). "Here we show that CD4+ TRM cells mediate control of the parasite burden within the first three days of infection, which correlates with a strong delayed-type hypersensitivity (DTH) response, the hallmark of immunity in murine and human leishmaniasis." (PMID 28419151, 2017). "Administration of killed P. acnes as an adjuvant increased the resistance to infection by T. cruzi and in leishmaniasis this adjuvant was used in murine vaccination with native and recombinant antigens resulting in protective immunity mediated by CD4+ Th1 lymphocytes." (PMID 28321209, 2017). "Altogether, our data suggest how the PD-1/PD-L axis could modulate Lm host cells and CD4+ T-cells in patients suffering from chronic forms of leishmaniasis." (PMID 29312350, 2017). "In preliminary experiments, we suggested the participation of CD4+ T cells to produce Interferon-gamma in LaAg vaccine, as indicated for several studies as the most important Th1 parasitic-specific response against leishmaniasis." (PMID 27716449, 2016). "We predict that this difference is due to the absence of regulatory T cells (Tregs) since in tumor models Tregs control the cytotoxicity of CD8+ T cells in a TGF-β dependent manner, and in leishmaniasis both CD4+ Th1 cells and CD4+ T regulatory cells (Treg) dampen the immune response." (PMID 23874205, 2013). "In leishmaniasis, macrophages, CD4+ T regulatory cells and CD4+ Th1 cells produce IL-10, although the relative importance of each of these sources is debated and may change as the infection progresses." (PMID 23555256, 2013).